MAN1A2 (mannosidase alpha class 1A member 2)
Description:
Involved in the maturation of Asn-linked oligosaccharides. Progressively trim alpha-1,2-linked mannose residues from Man(9)GlcNAc(2) to produce Man(5)GlcNAc(2).
Synonyms: MAN1B
Tractability: Antibody: UniProt predicts a signal peptide or a membrane-spanning region. PROTAC: ubiquitination databases record sites on it; its protein half-life has been measured.
Gene: Protein-coding gene on chromosome 1 (117,367,449 to 117,528,872, forward strand). Ensembl gene ENSG00000198162.
Subcellular location: Golgi apparatus membrane
Subcellular location (Human Protein Atlas): Golgi apparatus
Pathways (Reactome):
Metabolism of proteins: Progressive trimming of alpha-1,2-linked mannose residues from Man9/8/7GlcNAc2 to produce Man5GlcNAc2
Vesicle-mediated transport: Intra-Golgi traffic
Gene Ontology:
Molecular function: mannosyl-oligosaccharide 1,2-alpha-mannosidase activity; calcium ion binding
Biological process: ERAD pathway; Golgi apparatus N-glycan mannose trimming; N-glycan processing; carbohydrate metabolic process
Cellular component: extracellular exosome; Golgi apparatus; membrane; endoplasmic reticulum; Golgi membrane
Genetic constraint (gnomAD): Loss-of-function variants: 12 observed, 37 expected, observed/expected ratio (o/e) 0.32, 90% interval 0.21 to 0.52. The upper end of that interval is the gene's LOEUF score, 0.52, which puts it in group 2 of 6, group 1 being the genes least tolerant of losing a copy. Missense variants: 361 observed, 490.42 expected, observed/expected ratio (o/e) 0.74, 90% interval 0.68 to 0.8. Synonymous variants: 157 observed, 175.78 expected, observed/expected ratio (o/e) 0.89, 90% interval 0.78 to 1.02.
Homologues: Orthologues: chimpanzee MAN1A2 (99% identical), macaque MAN1A2 (98% identical), dog MAN1A2 (97% identical), guinea pig MAN1A2 (97% identical), pig MAN1A2 (96% identical), rat Man1a2 (95% identical), rabbit MAN1A2 (95% identical), mouse Man1a2 (95% identical), tropical clawed frog man1a2 (84% identical), zebrafish man1a2 (83% identical), Drosophila melanogaster alpha-Man-Ia (46% identical), Caenorhabditis elegans mans-2 (41% identical), and 3 more. Paralogues in human: MAN1A1 (62% identical), MAN1C1 (51% identical), MAN1B1 (32% identical), EDEM2 (24% identical), EDEM1 (24% identical), EDEM3 (23% identical).
Diseases named in the same sentence as MAN1A2 in open-access papers:
MAN1A2 is named in the same sentence as 32 diseases in open-access papers, as found by Europe PMC text mining. Sharing a sentence is not in itself a finding about the gene and the disease. The quoted sentences say what the papers report.
respiratory failure (2 papers, 2020 to 2021). The significant impairment of gas exchange within the lungs resulting in hypoxia, hypercarbia, or both, to the extent that organ tissue perfusion is severely compromised. "A previously reported homozygous deletion in the Man1a2 gene causes lethal respiratory failure in newborn pups and decreased lung ciliation compared with wild type (WT) pups." (PMID 34366878, 2021). "Recently, we have shown that Man1a2−/− newborn pups which are known to develop lethal respiratory failure due to homozygous deletion of the second Man1a2 exon, also showed poor lung ciliation, and abnormal biliary epithelial proliferation." (PMID 34366878, 2021). "We confirmed that compared with Man1a2+/+ WT mice, Man1a2–/– null mice exhibit unexpanded alveoli, thick interalveolar lung septa, and respiratory failure, and a grossly normal liver." (PMID 33192543, 2020). "Man1a2–/– mice, which experience respiratory failure, also demonstrated portal and bile ductular inflammation." (PMID 33192543, 2020).
acute lymphoblastic leukemia (1 paper, 2013). Leukemia with an acute onset, characterized by the presence of lymphoblasts in the bone marrow and the peripheral blood. "These specific inversions in MAN1A2 are described as post-transcriptional exon-shuffling RNAs and found highly expressed in several acute lymphoblastic leukemia samples." (PMID 23537109, 2013).
Alagille syndrome (1 paper, 2020). "MAN1A2 immunostaining revealed a diffuse cytoplasmic, peri-canalicular granular staining pattern in normal liver tissue and in diseased liver with Alagille’s syndrome and familial intrahepatic cholestasis, examples of childhood cholestatic diseases." (PMID 33192543, 2020).
atherosclerosis (1 paper, 2015). A disease characterized by the build-up of fatty material and calcium deposition in the arterial wall resulting in partial or complete occlusion of the arterial lumen. "The MAN1A2 gene, which was in this gene set, was reported to be down-regulated by TNFα and is part of an inflammatory mechanism in the pathological process of atherosclerosis." (PMID 25958224, 2015).
B cell lymphoma (1 paper, 2021). "Although the involvement of α-1,2 mannosidases has been reported in cancer, their role is still unclear: MAN1A2 has been included among prognostic indicators for to B cell lymphoma." (PMID 33925480, 2021).
biliary atresia (1 paper, 2024). A rare, biliary tract disease characterized by progressive obliterative cholangiopathy of the intra- and extrahepatic bile ducts, occurring in the embryonic/ perinatal period, leading to severe and persistent neonatal jaundice and acholic stool. "The most significant finding for bulk was linked to the gene MAN1A2 (P = 1.96 × 10–9, q = 0.015), a susceptibility gene for biliary atresia in neonates." (PMID 38778395, 2024).
breast carcinoma (1 paper, 2013). "CRAC detects three such chRNAs within the MAN1A2 gene, which recur in up to three out of four breast cancer libraries, and in a K562 library." (PMID 23537109, 2013).
ciliopathies (1 paper, 2021). "Defective glycosylation of ciliary proteins like Jbt17, which is performed by enzymes such as Man1a2 can lead to ciliopathies." (PMID 34366878, 2021).
esophageal squamous cell carcinoma (1 paper, 2023). Esophageal squamous cell carcinoma (ESCC) is a type of esophageal carcinoma (EC) that can affect any part of the esophagus, but is usually located in the upper or middle third. "HNRNPUL1 suppresses cisplatin (CDDP) sensitivity of esophageal squamous cell carcinoma cells by regulating the formation of MAN1A2, a cyclic RNA (circRNA) that suppresses CDDP sensitivity." (PMID 37484809, 2023).
esophageal ulcer (1 paper, 2024). An ulcerated lesion in the esophageal wall. "Thyrotoxicosis, psychotic depression, tympanosclerosis, vascular dementia, and esophageal ulcers showed the highest genetic correlations with MAN1A2." (PMID 39770468, 2024).
influenza (1 paper, 2023). An acute viral infection of the respiratory tract, occurring in isolated cases, in epidemics, or in pandemics; it is caused by serologically different strains of viruses (influenzaviruses) designated A, B, and C, has a 3-day incubation period, and usually lasts for 3 to 10 days. "During severe influenza, MAN1A2 was also downregulated and predicted to be highly regulated by miRNA." (PMID 37398192, 2023).
muscular dystrophy (1 paper, 2025). Muscular dystrophy (MD) refers to a group of more than 30 genetic diseases characterized by progressive weakness and degeneration of the skeletal muscles that control movement. "Reducing MAN1A2 expression, which involves the removal of sialic acid, was shown to alleviate muscular dystrophy symptoms, suggesting its potential importance in finishing precocity." (PMID 40370699, 2025).
tongue SCC (1 paper, 2014). "Of the 8 lncRNA, lnc-PPP2R4-5, lnc-SPRR2D-1, lnc-MAN1A2-1, lnc-FAM46A-1, lnc-MBL2-4:1, and lnc-MBL2-4:3 were upregulated in the microdissected tongue SCC tissues." (PMID 25045670, 2014).
type 2 diabetes (1 paper, 2017). "rs907662 on chromosome 1 potentially regulates Mannosidase, Alpha, Class 1A, Member 2 (MAN1A2), previously identified as being differentially expressed in type 2 diabetes patients compared with normal controls." (PMID 27864402, 2017).
cancer (5 papers, 2017 to 2025). A tumor composed of atypical neoplastic, often pleomorphic cells that invade other tissues. "Beyond its role in RLS, MAN1A2 has been implicated in broader biological processes and diseases, especially cancers, where it serves as a potential biomarker." (PMID 39770468, 2024). "Additionally, increased expression of oligomannoses in cancer has been linked to reduced expression or activity of α1,2-mannosidases, such as MAN1A1, MAN1A2, and MAN1C1." (PMID 40430030, 2025). "Shared inflammatory pathways, such as their regulation by TNF-α, may connect MAN1A2 to immune-related mechanisms common to both cancers and RLS." (PMID 39770468, 2024).
infection (1 paper, 2022). The state of being infected such as from the introduction of a foreign agent such as serum, vaccine, antigenic substance or organism. "Using a LCMV-pseudotyped virus and an infection period of 3 weeks, the authors identified seven host factors important for LCMV entry, four of which (CD164, ST3GAL4, SLC35A1, and MAN1A2) were contained within the set of 37 factors identified in our live virus screen." (PMID 35502904, 2022).
MAN1A2 also shares sentences with these, for which no sentence is quoted: autoimmune disease (1 paper); congenital heart disease (1); diabetes (1); Duchenne muscular dystrophy (1); familial intrahepatic cholestasis (1); hereditary optic neuropathy (1); Intellectual disability (1); lung adenocarcinoma (1); neurodevelopmental disorder (1); prostate carcinoma (1); psychotic depression (1); Pulmonary hypoplasia (1); thyrotoxicosis (1); tumor (1); tympanosclerosis (1); vascular dementia (1).